ENSG00000250424 (novel protein, MINDY4 and AQP1 readthrough)
Gene: Protein-coding gene on chromosome 7 (30,852,273 to 30,923,812, forward strand). Ensembl gene ENSG00000250424.
Genetic constraint (gnomAD): Loss-of-function variants: 30 observed, 46.75 expected, observed/expected ratio (o/e) 0.64, 90% interval 0.48 to 0.87. Missense variants: 548 observed, 610.52 expected, observed/expected ratio (o/e) 0.9, 90% interval 0.84 to 0.96. Synonymous variants: 251 observed, 259.82 expected, observed/expected ratio (o/e) 0.97, 90% interval 0.87 to 1.07.